FOXO3 (forkhead box O3)
Diseases named in the same sentence as FOXO3 in open-access papers (continued):
Sharing a sentence is not in itself a finding about the gene and the disease.
osteosarcoma (19 papers, 2014 to 2025). A usually aggressive malignant bone-forming mesenchymal neoplasm, predominantly affecting adolescents and young adults. "Additional predicted targets of miR-30a and miR-30e within this pathway include PIK3CA, mTOR, FOXO3, MMP13, SOX9, BCL2, VEGFA, and CCND1, all of which have been previously associated with osteosarcoma pathogenesis." (PMID 40862758, 2025). "In the development of chemotherapeutic drugs, several drugs, such as mitoxantrone, acetylshikonin and Brazil Lin, have been found to promote FOXO3-dependent cell death in osteosarcoma cells." (PMID 36823640, 2023). "MTX appears to induce apoptosis in osteosarcoma cells through the regulation of the Akt/FOXO3 pathway." (PMID 33784323, 2021). "By analyzing the molecular mechanisms, the authors demonstrated that tomentosin-induced ROS upregulate FOXO3 and p27 expression, thus suggesting that FOXO3 upregulation controls G2/M phase cell cycle arrest through p27 overexpression after tomentosin treatment in an osteosarcoma cell line." (PMID 36359261, 2022). "Conversely, the level of expression of the targets in the context of osteosarcoma-derived cells might limit their effect on FOXO3." (PMID 36080182, 2022). "Taken together, these results suggest that the anticancer activity of I3C treatment may rest on the induction of FOXO3-mediated apoptotic signaling pathways, and its application may lead to a novel therapeutic agent for osteosarcoma." (PMID 30627573, 2018). "In this study, we investigated the involvement of FOXO3 in I3C-mediated apoptosis of MG-63 and U2OS osteosarcoma cells." (PMID 30627573, 2018). "While we cannot rule out that the cellular context in the osteosarcoma-derived cell line limits the impact of the MAPK/ERK pathway on FOXO3, the MAPK inhibitors used in the experiments have been seen to affect MAPK signaling in U2OS cells." (PMID 36080182, 2022). "Thus, the study indicates that I3C may induce apoptosis in human osteosarcoma MG-63 and U2OS cells via the activation of apoptotic signaling pathways by FOXO3." (PMID 30627573, 2018).
rheumatoid arthritis (19 papers, 2015 to 2025). A chronic, systemic autoimmune disorder characterized by inflammation in the synovial membranes and articular surfaces. "SNPs in FOXO3 were shown in previous studies to be associated with ameliorated clinical course of rheumatoid arthritis, Crohn ́s disease and viral myocarditis." (PMID 33953705, 2021). "Several studies have shown that FOXO3 rs12212067 is associated with the clinical course of inflammatory diseases such as Crohn’s disease or rheumatoid arthritis." (PMID 32970737, 2020). "However, a SNP in FOXO3 resulting in increased expression of FOXO3 in monocytes during inflammatory conditions is associated with reduced disease severity in patients with rheumatoid arthritis (RA)." (PMID 25969990, 2015). "Genetic variation in FOXO3 (tagged by rs12212067) has been associated with a milder course of rheumatoid arthritis (RA) and shown to limit monocyte‐driven inflammation through a transforming growth factor β1–dependent pathway." (PMID 27214848, 2016). "Downregulation of FOXO3 expression is an important signal that impaired/inhibited autophagy and cellular senescence promote rheumatoid arthritis." (PMID 40238799, 2025). "FOXO3 is an key biomarker of cellular senescence and autophagy mechanisms involved in rheumatoid arthritis." (PMID 40238799, 2025). "Upregulation of FoxO3 has been observed in polymorphonuclear cells and peripheral blood mononuclear cells in patients with rheumatoid arthritis (RA)." (PMID 36233176, 2022). "Higher expression of SIRT1 and FOXO3 has been reported in diabetic patients and in rheumatoid arthritis synovial fibroblasts." (PMID 35153741, 2021). "In support of this premise, the minor allele of FOXO3 SNP rs12212067 (which is in linkage disequilibrium with rs2802292 and could act as a proxy) was associated with a milder clinical course of seemingly unrelated inflammatory conditions (Crohn's disease and rheumatoid arthritis)." (PMID 27071935, 2016). "Additionally, 14-3-3η has been implicated in the ECM degradation of fibroblast-like synovial cells in rheumatoid arthritis by facilitating the nuclear export of FOXO3." (PMID 41203613, 2025). "Furthermore, FOXO3 has been found to be overexpressed in polymorphonuclear cells from patients with rheumatoid arthritis." (PMID 25969990, 2015). "Taurine may serve as a promising therapeutic drug for rheumatoid arthritis by targeting FOXO3." (PMID 40238799, 2025). "Furthermore, paeonol, by upregulating forkhead box O3 (FOXO3) through inhibition of miR-155 expression, protects against TNF-α-induced proliferation and cytokine release of rheumatoid arthritis fibroblast-like synoviocytes." (PMID 32774428, 2020).
cardiomyopathy (18 papers, 2014 to 2025). A disease of the heart muscle or myocardium proper. "Besides, FoxO3 modulated DOX cardiomyopathy associated with the autophagy‐related gene LC3B, p62 and Beclin 1, as well as mTOR signalling in vivo and in vitro." (PMID 40785055, 2025). "Altogether, these results further demonstrated that FoxO3 protected against DOX‐induced cardiomyopathy through increasing autophagy and suppressing ROS/mTOR activity." (PMID 40785055, 2025). "Mechanistically, we demonstrated that FoxO3 protected against doxorubicin‐induced cardiomyopathy by activating autophagy in vivo and in vitro." (PMID 40785055, 2025). "Taken together, these data indicated that the FoxO3 signalling pathway was related to DOX‐induced cardiomyopathy in mice." (PMID 40785055, 2025). "Our data revealed that Foxo3 overexpression significantly reduced lipid accumulation and alleviated cardiomyopathy in the presence of Piezo1 GOF." (PMID 41237237, 2025). "In the present study, we revealed a previously uncovered role of FoxO3 in doxorubicin‐induced cardiomyopathy." (PMID 40785055, 2025). "In cardiomyopathy, it has been reported that circ-Foxo3 interacts with anti-senescent proteins ID-1 and E2F1, as well as anti-stress proteins FAK and HIF1α, leading to the relocation of these proteins in cytoplasm." (PMID 38360615, 2024). "In a TAC-induced mouse model of cardiomyopathy induced by pressure overload, high circ Foxo3 expression was found to be involved in the protective mechanism of Ganoderma spore oil against cardiomyopathy." (PMID 36952519, 2023). "In vitro, the ectopic expression of circ-Foxo3 induced senescence in fibroblasts; on the other hand, in vivo, the silencing of circ-Foxo3 reduced doxorubicin-induced cardiomyopathy in mice." (PMID 36902000, 2023). "Although, a similar type of cardiomyopathy accompanied with muscle wasting was observed when FOXO3 was over-expressed, our RNAseq data suggested that the level of Foxo3 was not increased in the HD murine hearts." (PMID 25101683, 2014). "Therefore, enhanced autophagy maintains cellular homeostasis and reduces the accumulation of reactive oxygen species, which is a crucial mechanism by which FoxO3 protects against DOX cardiomyopathy by activating autophagy." (PMID 40785055, 2025). "Considering the cardioprotective effects of FoxO3, we believe that it is worthy of additional molecular investigation in order to discover more effective and selective derivatives for use as the treatment of cardiomyopathy triggered by DOX." (PMID 40785055, 2025). "Collectively, targeting FoxO3 to enhance protective autophagy may offer a therapeutic strategy against DOX‐induced cardiomyopathy." (PMID 40785055, 2025). "Meanwhile, circ-Foxo3 expression level is upregulated in aged patient and mice tissues, overexpression of circ-Foxo3 contributes to the progression of senescence in mice Dox-induced cardiomyopathy cells by interacting with ID1, E2F1, FAK, and HIF1A." (PMID 28219405, 2017). "Subsequently, to further discover the mechanism of FoxO3 in DOX‐induced cardiomyopathy, we next constructed an adenoviral FoxO3 overexpression system (AAV9‐OEFoxO3) to achieve heart‐specific FoxO3 overexpression." (PMID 40785055, 2025). "While numerous studies have clarified the function of FoxO3, its roles in DOX‐induced cardiomyopathy as mediated by FoxO3 remain unclear, and many mechanisms have yet to be identified." (PMID 40785055, 2025). "Based on our research, overexpression of FoxO3 enhances autophagy, inhibits oxidative stress and mTOR activation in the doxorubicin model; we propose that FoxO3 initiates autophagy, resulting in a favourable outcome that mitigates the effects of DOX‐induced cardiomyopathy." (PMID 40785055, 2025). "Our in vivo studies suggest that the cardioprotective effect of FoxO3 may lie in the activation of autophagy and depend on the mTOR pathway in DOX‐induced cardiomyopathy." (PMID 40785055, 2025).
cardiomyopathy (continued). "Conversely, AC5 disruption protects the heart from the cardiomyopathy induced by chronic pressure overload and catecholamine stress, and leads to better exercise performance, most likely due to preserved SIRT1 and FoxO3 activity and MnSOD levels." (PMID 33671541, 2021). "However, the relationship between FoxO3 and the mTOR signalling pathway in DOX‐induced cardiomyopathy remains unclear." (PMID 40785055, 2025).
Hypertension (18 papers, 2014 to 2026). The presence of chronic increased pressure in the systemic arterial system. "Clinical studies have observed that individuals with the FOXO3 rs2802292 longevity genotype have a lower risk of hypertension and dementia in old age, suggesting a protective role of FOXO3 against vascular aging." (PMID 41180381, 2025). "The present study found that the FOXO3 longevity-associated genotype strongly protects against incident CAD in men with hypertension." (PMID 39497655, 2024). "In contrast, in subjects with hypertension, a strong association was found between FOXO3 G-allele carriage and protection against incident CAD." (PMID 39497655, 2024). "Our findings support the feasibility of stratifying middle-aged men by FOXO3 genotype and hypertension status in assessing their risk of CAD." (PMID 39497655, 2024). "The longevity-associated genetic variants in FOXO3 are associated with a mortality risk reduction for coronary heart disease and with blood pressure and essential hypertension reduction in American women." (PMID 39273459, 2024). "Associations between FOXO3 rs2802292 and the prevalence of essential hypertension and improved metabolic control in diabetic patients have been shown in previous studies." (PMID 36143124, 2022). "Longevity-associated genetic variants of FOXO3 are also associated with lower blood pressure and reduced hypertension prevalence." (PMID 33260156, 2020). "The data suggest a possible mediator role for hypertension, which we found to be less prevalent in middle‐aged women carrying the FOXO3 G allele." (PMID 27071935, 2016). "This study tested whether the carriage of the longevity-associated G-allele of FOXO3 SNP rs2802292 (TG/GG) protects against incident coronary artery disease (CAD) in men with hypertension." (PMID 39497655, 2024). "The longevity genotype of FOXO3 single nucleotide polymorphism (SNP) rs2802292 has shown a resilience effect on mortality in response to stress in those who have a cardiometabolic disease (namely, hypertension, prevalent CAD, and/or diabetes)." (PMID 39497655, 2024). "The longevity-related FOXO3 polymorphisms may be associated with lower blood pressure (BP) in Japanese women with hypertension." (PMID 35004893, 2021). "Of particular interest, in multivariable models of mortality risk factors, five of the top risk factors for mortality at older ages (i.e. smoking, hypertension, fasting glucose, low BMI, low cholesterol) had little influence on the effect on mortality of FOXO3 genotype in Japanese men." (PMID 27071935, 2016). "It further shows an interaction effect between hypertension status and FOXO3 genotype on CAD incidence in the cohort." (PMID 39497655, 2024). "The stratified differences suggested an interaction effect between FOXO3 genotype and hypertension status in relation to CAD incidence." (PMID 39497655, 2024). "The results of the present studies clearly indicate that chronic stress leads to manifest arterial hypertension and cerebral effects such as increased ROS production and downregulation of nNOS and FOXO3." (PMID 35174211, 2021). "We reported previously that the FOXO3 rs2800292G allele was associated with reduced risk of hypertension in women, but not men, from a cohort of Japanese individuals living in Japan." (PMID 33260156, 2020). "Furthermore, it may be worthwhile formulating a FOXO3 genotype- and hypertension-specific CAD prevention program to reduce incident CAD, specifically in middle-aged men with the FOXO3 TT genotype." (PMID 39497655, 2024). "However, the sensitivity analyses showed when CAD deaths, which accounted for 11.5% percent of incident CAD cases, were removed from the analysis, the effect of FOXO3 genotype in moderating the effect of hypertension on incident CAD remained unchanged (row B and 5, row B)." (PMID 39497655, 2024).
Hypertension (continued). "In studies of FOXO3, MAP3K5, PIK3R1, GHR, and FLT1 we found that for each, the genetic variants associated with longer lifespan may activate cell resilience mechanisms, leading to amelioration of the adverse effects of hypertension." (PMID 37561089, 2023). "In the current study, we hypothesized that exercise and DF administration might ameliorate hypertension in the SHR model and, if so, the anti-hypertensive effects of DF and exercise may be partly due to the regulation of the AMPK/SIRT1/PGC-1α/FOXO3 pathway." (PMID 35890118, 2022). "DF peptides and exercise act synergistically and attenuate the myocardial injury induced by spontaneous hypertension, possibly by regulating the energy metabolism signaling pathway (AMPK/SirT1/PGC-1α/FOXO3), as well as preventing myocardial fibrosis, hypertrophy, and apoptosis." (PMID 35890118, 2022). "Besides, longevity-promoting resilience genes like FLT1, Foxo3, GHR3, MAP3K5, PIK3R1 could mitigate mortality from hypertension, which further indicating the genetic influences in hypertension and vascular aging." (PMID 41507140, 2026). "The significant interaction of hypertension with FOXO3 genotype in the Japanese-ancestry cohort and the Kuakini HHP cohort in the full models indicated that the effect of FOXO3 genotype on incident CAD differed between subjects with and without hypertension." (PMID 39497655, 2024).
type 2 diabetes (18 papers, 2010 to 2025). "Moreover, the rs2802292 G-allele of FOXO3 is associated with lower blood glucose levels in older women with type 2 diabetes in East China." (PMID 39273459, 2024). "In this context, metformin, a biguanide drug that has long been used to treat type 2 diabetes due to its robust glucose-lowering effects, well-established safety profile, and relatively low cost, is known to activate the AMPK- and FOXO3-dependent pathways." (PMID 40869969, 2025).
viral infection (18 papers, 2012 to 2025). "A deficiency in FoxO3 following a viral infection has been shown to facilitate considerably exaggerated expansion of T-cell populations." (PMID 36233176, 2022). "A deficiency in FoxO3, following a viral infection, was shown to facilitate considerably exaggerated expansion of T-cell populations." (PMID 34102081, 2021). "Interestingly, in other virus infection systems, FOXO3 suppression is linked to antiviral responses." (PMID 33853871, 2021). "YTHDF3 promotes the translation of a transcription repressor named forkhead box protein O3 (FOXO3) upon viral infection." (PMID 41019992, 2025). "The levels of active unphosphorylated FOXO3 are also increased due to the inactivation of PI3K/Akt pathway (due to decreased viral infection upon compound PI-7)." (PMID 38816514, 2024). "Studies indicate that FoxO transcription factors such as FoxO1 and FoxO3 regulate immune responses to viral infections." (PMID 38674337, 2024). "By potentially reducing the expression of inflammatory cytokines in response to viral infections, FoxO3 activation provides protection against lung inflammation." (PMID 36233176, 2022). "By using cells with a genetic deletion of FoxO3a, we observed an increase in virus infection in the FoxO3−/− cells as compared to the FoxO3a+/+ cells." (PMID 34650053, 2021). "Since CIITA has been implicated in resisting the endosomal entry of SARS-CoV-2, modulation of the FoxO3- CIITA signalling is likely to aid in managing the viral infection." (PMID 34102081, 2021). "As for the potential role of miRNAs in the regulation of FoxO3, miR223 was reported to inhibit the expression of FoxO3 in a viral infection model." (PMID 32630045, 2020). "Another viral infection model also showed an inhibitory effect of miR-155 on the expression of FoxO3." (PMID 32630045, 2020). "Thus, activation of FoxO3 potentially alleviates the expression of pro-inflammatory cytokines in response to viral infection, thus imparting protection against lung inflammation." (PMID 34102081, 2021). "miR223 and miR155 are upregulated by viral infection, leading to the suppression of FoxO3." (PMID 32630045, 2020). "Notably, prior research has shown that Foxo3 protein undergoes stress-induced degradation, raising the possibility that viral infection may disrupt the Med23-Foxo3 interaction." (PMID 40705824, 2025). "In contrast, FoxO3 suppresses DC production of key inflammatory cytokines, such as IL-6 and TNF, and constrains CD4+ and CD8+ T-cell population expansion after viral infection." (PMID 36233176, 2022). "In the present study, we have systematically examined the T cell-intrinsic role of FOXO3 in controlling the expansion, contraction, and memory phases of the polyclonal CD8 T cell response to an acute viral infection." (PMID 22359505, 2012). "By limiting the transcription of IRF7, FOXO3 thus prevents leakiness in IFN signaling in the absence of viral infection." (PMID 39995872, 2025). "To test this hypothesis, we analyzed the expression of FoxO1 and FoxO3 in response to the immunostimulants poly (I:C) and IFN-β, which mimic viral infection and elicit an antiviral response, respectively." (PMID 36016282, 2022). "However, the T cell intrinsic role of FOXO3 in regulating various phases of the polyclonal multi-epitope-specific CD8 T cell response to an acute viral infection in lymphoid and non-lymphoid organs remains to be determined." (PMID 22359505, 2012).